RNU6-1155P (RNA, U6 small nuclear 1155, pseudogene)
Gene: Small nuclear RNA gene on chromosome 16 (58,744,251 to 58,744,357, reverse strand). Ensembl gene ENSG00000200424.
Homologues: Orthologues: chimpanzee U6 (99% identical), macaque U6 (97% identical), dog U6 (85% identical). Paralogues in human: RNU6-621P (88% identical), RNU6-1079P (87% identical), RNU6-1152P (87% identical), RNU6-1316P (87% identical), RNU6-142P (87% identical), RNU6-19P (87% identical), RNU6-35P (87% identical), RNU6-12P (86% identical), RNU6-13P (86% identical), RNU6-166P (86% identical), RNU6-25P (86% identical), RNU6-26P (86% identical), and 1288 more.